TF (transferrin)
Diseases named in the same sentence as TF in open-access papers (continued):
Sharing a sentence is not in itself a finding about the gene and the disease.
tumor (continued). "For example, binding of galectin-3 to the oncofoetal Thomsen-Friedenreich Galβ1,3GalNAcα-Thr/Ser (TF antigen) on the transmembrane mucin protein MUC1 enhances circulating tumour cell homotypic aggregation and survival and increases tumour cell heterotypic adhesion to vascular endothelium." (PMID 37055381, 2023). "vivo optical imaging showed broad distribution of labeled transferrin, with high levels in lungs, liver, and kidneys, for both non-tumor and tumor mice." (PMID 38117806, 2023). "SNAIL is also a TF which controls EMT during embryogenesis and tumor progression." (PMID 36431925, 2022). "CALLA-01, a targeted NP system, consists of cyclodextrin-containing polymer, polyethylene glycol (PEG), human transferrin as a targeting ligand for binding transferrin receptors, and siRNA designed to reduce expression of RPM2 for tumor inhibition and/or tumor size reduction." (PMID 35057033, 2022). "When enhancing the adhesion ability of the extracellular matrix (including laminin, collagen, and fibronectin), TF MYBL2 is upregulated to promote the activity of epithelial–mesenchymal transition (EMT), enabling tumor cells to acquire the characteristics of migration and invasion." (PMID 35164166, 2022). "It is worth mentioning that two proteins indicated by this pathway, LDH and TF, were upregulated in the center, whereas a third, PKM, was upregulated in the margin, which may reflect the metabolic specificity of the tumor parts." (PMID 35512017, 2022). "TF peptide guides the nanoparticle to TfR overexpressing malignant tumor cells and cathepsin B control the release of ART and buthionine-sulfoximine to increase ROS production, decrease GSH levels and thus induce tumor cell death." (PMID 35214127, 2022). "The transferrin-modified SPIONs (Tf-SPIONs) were combined with CTNF-α-exosomes to prepare drug-loaded exosomes, which significantly enhanced the growth inhibition of tumor cells." (PMID 35198064, 2022). "To achieve this, we generated two unique vectors (floxed-pSico-CD44v6 shRNA plus Fabpl-Cre) that were encapsulated into transferrin coated PEG-PEI/(nanoparticles), which when introduced in vivo reduced tumor growth more effectively than using CD44v6-blocking antibodies." (PMID 35982950, 2022). "In particular, a detailed investigation was performed of the use of drug co-loaded (DOX and erlotinib) liposomes modified with transferrin (Tf) for receptor-mediated endocytosis and a cell-penetrating peptide, penetratin (Pen), against GBM, using tumor mice model." (PMID 36109754, 2022). "At diagnosis, most patients presented with comparable biochemical levels of serum proteins (transferrin, albumin, ferritin, prealbumin and reactive C protein (RCP)), lipids (total and fractionated cholesterol) and lymphocytes, considering the primary tumor site." (PMID 35008278, 2021). "GBM cancer-stem-like cells were shown to upregulate transferrin expression, and to extract iron more effectively from the tumor microenviroment than non-stem-like tumor cells in an ex vivo explant model." (PMID 33842321, 2021). "These transferrin-modified micelles showed cytotoxicity against ovarian carcinoma cells, A2780, and inhibited tumor growth on A2780 tumor-bearing mice compared to non-drug and non-modified micelles." (PMID 34142021, 2021). "Here, we report the novel dual-targeting ruthenium candidate 2b, which has both antitumor and antimetastatic properties and targets tumor sites through the enhanced permeability and retention (EPR) effect and transferrin/transferrin receptor (TF/TFR) interaction." (PMID 33892746, 2021). "LTSLs have displayed their fantastic safety and biocompatibility in our previous study and we did not observe significant cytotoxicity induced by TF during our in vitro anti-tumor efficacy study." (PMID 34959271, 2021). "In support of this idea, we found that TF is not co-localized with TAMs in tumor tissue from Hepa1-6-bearing mice." (PMID 34389031, 2021).
tumor (continued). "For example, dynamic PET imaging data from a 64Cu-labelled and transferrin-targeted cyclodextrin NP, applied to a compartmental model of tumor uptake, showed that bulk tumor targeting is not affected by ligand functionalization." (PMID 31938046, 2020). "We demonstrated increased uptake of radiolabelled neutrophils from the blood into tumours compared with non-specific uptake using radiolabelled transferrin." (PMID 32887739, 2020). "Yet in the same study, bioluminescence imaging demonstrated that transferrin-targeted NP containing siRNA attenuated tumor cell luciferase expression better than non-targeted NP." (PMID 31938046, 2020). "Tumor cells increase iron uptake through the upregulation of divalent metal transporter-1 (DMT1), transferrin/transferrin-receptor (Tf/TfR), and lipocalin-2/lipocalin-2receptor (Lcn-2/Lcn-2R) systems, and its storage by ferritin (FT) heavy chain (FTH) and FTL overexpression." (PMID 32426284, 2020). "Tumour uptake increased in patients with injected In-111-neutrophils with a median of 0.0038 mL/min/mL (IQR; 0.0231–0.0531) compared with a median of 0.0009 mL/min/mL for In-111-transferrin (IQR; 0.0004–0.0013)." (PMID 32887739, 2020). "Alternatively, transferrin-bound iron may be taken up via the transferrin receptor 1 (TFRC1), which is highly expressed in tumor cells." (PMID 31383898, 2019). "Temperature change has increased over repeated injection of transferrin in the tumor tissue but did not in normal subcutaneous tissues onto local radiofrequency hyperthermia." (PMID 30202000, 2018). "Although we could not identify the responsible genes that promoted transcription of CCNA1 and CCNA2, we found that positive correlation between FOXP3 as TF and CCNA2 as TG is disrupted in tumor samples." (PMID 29504910, 2018). "I. v. injection of transferrin led to accumulation of ferric ion in the heart and liver also although ferric ion in the organs was not accumulated as much as in the tumor tissue." (PMID 30202000, 2018). "With ‘TF regulation’ checked, TF-TG correlation coefficients are provided and then user can get the TFs targeting CCNA1, CCNA2 and see that the correlation coefficient between FOXP3 and CCNA2 is much different in normal samples (0.58) and tumor samples (0.16)." (PMID 29504910, 2018). "These collectively suggest that PLAU might server as a significant TF promoting PTC progression, while EGR2 might be a tumor suppressor." (PMID 29351231, 2018). "Transferrin-conjugated micelles also showed enhanced cytotoxicity in vitro and an appreciable inhibition of tumor growth compared to drug loaded micelles lacking transferrin on their surface." (PMID 30671429, 2018). "Another TF, E2F1, promoted the apoptosis and acted as tumor suppressor." (PMID 29069717, 2017). "Studies with DNAzymes carried by the transferrin-cyclodextrin also support the notion that internalization within the tumor cell and not accumulation and localization within the tumor is the important factor." (PMID 29218233, 2017). "At the beginning of the primary culture of tumour cells from the patient ascites, cells grew in RPMI 1640 culture medium supplemented with 10% patient ascites, 10% foetal bovine serum (FBS), 10 ng/mL insulin, and 10 ng/mL of transferrin at 37 °C with 5% CO2." (PMID 28860565, 2017). "Accordingly, TF fusion proteins such as tTF-RGD are demonstrated to induce selective, fast and widespread thrombosis in tumor vasculature, leading to the rapid shutdown of tumor blood flow and subsequent necrosis and destruction of tumor cells." (PMID 28811469, 2017). "To add to the earlier proposed tumor specific transferrin-mediated uptake and redox activation of KP1019, we show that higher metal loads or altered ion homeostasis in tumor also selectively exaggerates KP1019 activity in cancerous cells compared to normal healthy cells." (PMID 29228701, 2017).
tumor (continued). "Neither glycans (SiaTn, Tn, TF, LeC, LeY, SiaLeA, and Manβ1‐4GlcNAcβ), nor tumor markers (CEA, CA19–9, CA 125, CA 15–3) used in this study have been previously reported to be specific to CRC." (PMID 26992329, 2016). "The results of in vivo tumor growth inhibition studies confirmed the enhanced efficacy of TF-modified 8arm-PEG-DHA NPs to non-modified and free DHA with low toxicity." (PMID 27377918, 2016). "The chlorin e6 fluorescence was weak in the crania of tumor-bearing mice injected with control platelets (ie those lacking transferrin)." (PMID 27049725, 2016). "The in vitro cytotoxicity and in vivo tumor growth inhibition studies in LLC-tumor bearing mice confirmed the enhanced efficacy of TF-modified 8arm-PEG-DHA NPs compared to free DHA and non-modified 8arm-PEG-DHA NPs." (PMID 27377918, 2016). "Firstly, AGA to seven out of the 22 investigated glycans significantly differentiated plasma samples from control women and HGSOC patients in the SGA: the two top AGA, anti-SiaTn and anti-6-OSulfo-TF, and CA125 (standard tumor marker commonly used in the clinics) distinguished with comparable power." (PMID 27764122, 2016). "Results revealed that transferrin- (Tf-) targeted nanoparticles containing two different siRNA sequences slowed the tumor growth, whereas the nontargeted nanoparticles were considerably less efficient, when treated at the same dose." (PMID 26582104, 2015). "The modified TF and RGD also could facilitate the transportation of LPs through C6 tumor spheroids, which was markedly better than LP alone." (PMID 25289086, 2014). "These properties of mdl-1 mutants recapitulate effects of Mad TFs in mammals, e.g. mice lacking the Mad TF Mxi1 show hyperplasia in a number of tissues (e.g. prostatic epithelium), and are tumor prone." (PMID 24531613, 2014). "Our results show that in the pathological skeletal remain several well known tumor biomarkers are detected such as annexin A10, BCL-2-like protein, calgizzarin, rho GTPase-activating protein 7, HSP beta-6 protein, transferrin and vimentin compared to the control samples." (PMID 24475253, 2014). "However, similar to the enhanced methylation category, we also (paradoxically) observed low methylation of some tumor suppressors, including the ONECUT and FOX (forkhead) family of TF genes." (PMID 22412954, 2012). "Despite their importance as specific tumour antigens, conjugates of Fmoc-β3hSer and Fmoc-β3hThr carrying larger TACA structures such as the Thomsen–Friedenreich antigen (TF) or its sialylated variants (α2-6sTF and α2-3sTF) have not been reported to date." (PMID 20563275, 2010). "Thus, the interaction between circulating galectin-3 and TF-expressing MUC1 on the surface of disseminating cancer cells promotes cell aggregation and embolus formation and enhances survival of disseminating tumour cells in the circulation." (PMID 20565834, 2010). "In our case we observed an avid uptake of 99mTc-TF that is explained by the high vascularity and metabolic activity of the tumor, but also by the lesion's absence of blood-brain barrier which allows leakage of the 99mTc-TF from the cells." (PMID 20062671, 2009). "Mechanistically, transferrin directly interacts with TRAC with a high affinity of 10.9 nM to interfere with TCR–CD3 complex interaction to suppress TCR activation and anti-tumor immunity, while blocking transferrin–TRAC interaction inhibited metastasis and showed significant anti-tumor effects." (PMID 39810853, 2025). "Other derivatives of BSH, such as BSH‐encapsulating and transferrin (TF)‐conjugated polyethylene glycol liposomes, can increase the uptake of boron in tumors and can be used as new targeted drugs for BNCT to treat cancer, inhibit tumor growth and improving survival." (PMID 41477294, 2025).
tumor (continued). "Preclinical models have shown strong anti-tumour responses in various solid malignancies: TF- or PD-L1-targeted CAR-NK cells in TNBC, c-Met CAR-NK cells with DAP10 co-stimulation in LUAD, and DLL3-specific CAR-NK cells in SCLC, which exhibited effective tumour suppression and immune infiltration." (PMID 40624498, 2025). "Non-tumor components included endothelial cells (expressing VWF, CDH5, ECSCR, SLCO2A1, and MYCT1), pericytes (marked by RGS5, MCAM, and PDGFRB), normal oligodendrocytes (showing PTGDS, MBP, TF, and MOG expression), and TAMs (identified by CD14, AIF1, FCER1G, FCGR3A, TYROBP, and CSF1R)." (PMID 41394801, 2025). "In this study, we identified a novel strategy that inhibits TCR activation, in which transferrin directly binds to TRAC to inhibit the formation of the TCR–CD3 signaling complex, block TCR signaling, and consequently suppress anti-metastatic and anti-tumor immunity." (PMID 39810853, 2025). "WL and transferrin did not correlate significantly with postoperative residual tumor." (PMID 38339372, 2024). "Several ligands, antibodies, or short peptide-modified nanocarriers, including transferrin, folic acid, and anti-CD47 antibodies, with high specificity and affinities have been developed, considering the specific high expression of receptors or protein antigens on tumor cell membranes." (PMID 38389925, 2024). "For example, MEF2A may play a dual role in promoting tumor proliferation and metastasis by inducing the activation of EMT and WNT/beta -catenin signaling, whereas TCF7L2 serves as a core TF of the WNT signaling pathway, and is involved in regulating tumor cell proliferation and migration." (PMID 39712016, 2024). "Moreover, we have shown significant differences in receptor-mediated endocytic trafficking pathways, iron metabolism-related processes and transferrin uptake into tumor xenografts between T47D and MDA-MB-231 in the absence of estrogen." (PMID 38184712, 2024). "Transferrin facilitated the accumulation of intracellular iron levels, while a pH-sensitive DOPE (dioleoylphosphatidylethanolamine) lipid layer enhanced cellular uptake, prevented early drug leakage, and enabled pH-responsive piperlongumine release in response to low pH at the tumor site." (PMID 36677534, 2023). "In mice carrying subcutaneous Neuro2A tumors, Choi and colleagues explored whether or not human transferrin (Tf) has an effect on the PEGylated gold nanoparticles (on tumor targeting)." (PMID 36707835, 2023). "Inhibited by TF MED17, target gene DNMT1 undergoes a DNA demethylation reaction, not only weakening its carcinogenicity but also contributing to a gradual slowdown of the cell proliferation rate and a promotion of apoptosis, which plays a crucial role prior to tumor cell metastasis." (PMID 35164166, 2022). "Liposomes can be actively guided for identification by receptors at the tumor location by synthetically altering the liposome surface or terminal PEG (polyethylene glycol) molecule with tumor-specific ligands, such as folic acid, transferrin, or monoclonal antibodies." (PMID 35957103, 2022). "In addition, the activation of the NOD1 receptor induced by IE-DAP could upregulate TF STAT1, acting as an active transcription factor to boost tumor metastasis in PCa and upregulate the target gene CD3G." (PMID 35164166, 2022). "In response to the acidic tumor microenvironment, the transferrin-modified MgO2 nanosheets rapidly generate a substantial amount of H2O2 and then undergo a Fenton reaction with metal released from transferrin, which substantially enhanced the production of toxic •OH for the effective cancer therapy." (PMID 36568636, 2022). "We used preclinical tumor models to confirm that 68Ga-citrate uptake is dependent on TFR expression and activity, which is consist with previous findings that 68Ga-citrate could bind to apo-TF in blood as an Fe (III) biomimetic." (PMID 36139668, 2022).
tumor (continued). "The bioluminescence (BLI) signals showed that Lipo-CD44-TF could specifically target the tumor by recognizing the CD44 antigen, while Lipo-TF/GCV does not target cancer cells." (PMID 35456655, 2022). "Although TF-MSCs also increased tumor invasion, they were not as effective as LC-MSCs." (PMID 33744858, 2021). "Binding of galectin-3 to TF on MUC1 of tumour cells induces MUC1 cell surface polarization and exposure of smaller cell surface adhesion molecules/ligands, leading to increase of tumour cell-endothelium adhesion and tumour cell–cell homotypic aggregation, two important steps in metastasis." (PMID 34223877, 2021). "Furthermore, attempts to use non-antibody peptides/proteins such as RGD (Arg-Gly-Asp), folate and transferrin have yielded non-specific results due to lack of disparity or receptor density in expression of their targets among tumor and normal tissues." (PMID 34577537, 2021). "Transferrin can be taken up by tumours non-specifically through highly permeable blood vessels." (PMID 32887739, 2020). "Hence, in two further patients, In-111-transferrin was prepared as a control for non-specific uptake, so that specific focal accumulation of In-111-neutrophils in the tumour area can be compared." (PMID 32887739, 2020). "For instance, transferrin conjugated to doxorubicin had enhanced cytotoxicity in drug-resistant leukemia cells compared to free drug, but did not accumulate normal human fibroblasts indicating improved tumor specificity." (PMID 32328462, 2020). "To prioritize the true lncRNA/TF regulatory pairs involved in tumors, we combined the results of co-expression and CIT and take advantage of pan-cancer dataset to define a confident list of pairs as those passed both co-expression test and CIT in more than two tumor types." (PMID 30229065, 2018). "For example, reduced DNA methylation in an enhancer region in a tumor cell relative to a normal cell could allow a TF to bind and regulate a target gene in a tumor-specific manner without changes in the expression level of that TF in the tumor." (PMID 25994056, 2015). "Indeed, transferrin targeting did not affect biodistribution, as both targeted and non-targeted particles accumulated to a similar extent in the tumor microenvironment (due to the enhanced permeability and retention effect) as well as in the liver and kidneys." (PMID 25550431, 2015). "The serum iron and transferrin saturation also did not change significantly in tumor-bearing mice." (PMID 25822717, 2015). "We also detected 147 gene fusions in non-tumor liver tissues, many of which involved genes with extremely high expression values in liver tissues, such as ALB, HP, and TF, suggesting that detected fusion transcripts may also have originated from SVs harbored within minor sub-clonal liver cells." (PMID 25526364, 2014). "The outcomes exhibited by transferrin surface modified liposomes increased the delivery of both drugs and inhibited multidrug resistance, extended half-life, higher intracellular uptake, reduced malignancy, decreased non-specific bio-distribution observed in tumour-bearing mice." (PMID 37552393, 2024). "In conclusion, plasma-derived AGA to sialylated and sulfated glycans including SiaTn and 6-OSulfo-TF detected by SGA present a valuable alternative to CA125 for differentiating controls from HGSOC patients and for predicting the likelihood of HGSOC, and may be potential HGSOC tumor markers." (PMID 27764122, 2016). "Finally, we provide useful information on numerous TF genes whose roles in colorectal tumorigenesis have been relatively unexplored, such as DACH1, a development gene whose protein expression patterns in colorectal tissues raises interesting questions about its involvement in tumor growth." (PMID 24472434, 2014).